RN7SL293P (RNA, 7SL, cytoplasmic 293, pseudogene)
Gene: Miscellaneous RNA gene on chromosome 8 (11,379,395 to 11,379,675, forward strand). Ensembl gene ENSG00000242483.
Homologues: Orthologues: chimpanzee Metazoa_SRP (99% identical). Paralogues in human: RN7SL296P (78% identical), RN7SL1 (78% identical), RN7SL2 (77% identical), RN7SL3 (76% identical), RN7SL5P (75% identical), RN7SL126P (75% identical), RN7SL566P (75% identical), RN7SL49P (75% identical), RN7SL4P (75% identical), Metazoa_SRP (74% identical), RN7SL336P (74% identical), RN7SL507P (74% identical), and 698 more.